MR1 (major histocompatibility complex, class I-related)
Diseases named in the same sentence as MR1 in open-access papers (continued):
Sharing a sentence is not in itself a finding about the gene and the disease.
cancer (continued). "Generation of cancer-reactive MR1-restricted T cell lines and clones from multiple donors." (PMID 39744940, 2025). "Here, we succeeded in generating similar cancer-activated MR1-restricted T cells from all donors." (PMID 39744940, 2025). "Thus, cancer cells that express the cancer antigen in the context of MR1 are vulnerable to destruction by matching T-cells." (PMID 40362653, 2025). "Clinical research has reported that MR1 expression in tumors varies significantly, with some cancers upregulating MR1 as a potential immune evasion strategy, correlating with poor prognosis, while others exhibit reduced MR1 expression, potentially limiting MAIT and diverse MR1T cell activation." (PMID 40746558, 2025). "In contrast with classical MHC-I molecules (over 10,000 alleles), MR1 shows very little inter-individual variability (only 6 allele groups;), which creates a huge opportunity for the application of MR1T cells in the therapy of bacterial infections and cancer." (PMID 40362653, 2025). "Further studies will be required to determine whether MR1-presented B6-related compounds are of relevance to MR1-restricted recognition of cancer cells." (PMID 40763744, 2025). "We next addressed claims made in a recent study, which suggested that recognition by cancer-reactive MR1-restricted TCRs, including MC.7.G5 and MC.27.759S, was restricted to the MR1*04 variant and was not cancer-specific." (PMID 39744940, 2025). "In humans, MR1-restricted T cells exhibit high clonal diversity, characterized by variant TCR chains, the recognition of cancer cells, and the potential ability to kill cancer cells." (PMID 40746558, 2025). "Interestingly, MR1-restricted T-cells that respond to cancer cells can be isolated from all donors tested." (PMID 40362653, 2025). "Sequencing of cancer-activated MR1-restricted T cells reveals a TRAJ42 bias." (PMID 39744940, 2025). "The results of a previous study contrasted with our own by finding that the MC.7.G5 and MC.27.759S TCRs did not respond to MR1*01 homozygous and MR1*01/*02 cancer cell lines, prompting us to consider what had caused this disparity." (PMID 39744940, 2025). "Notably, the MOC‐L1‐sh‐mR1#1 and MOC‐L1‐sh‐mR1#2 cells exhibited remarkable cancer regression compared with MOC‐L1‐sh‐Ctrl cells." (PMID 39932384, 2025). "The conservation of this public-like TCR motif across all but 1 donor we studied and the unusual, near ubiquitous, expression of the CD8-αβ isoform defines CAITs as a new T cell subset and suggests that they respond to a common MR1-restricted ligand on the surface of cancer cells." (PMID 39744940, 2025). "We recently found that MR1-restricted cancer-activated T cells could be cultured from the peripheral blood mononuclear cells (PBMCs) of all healthy individuals tested." (PMID 40763744, 2025). "MR1 is also thought to be able to present ligands at the surface of cancer cells." (PMID 40763744, 2025). "For example, they can suppress T and NK cells and blocking the MR1 protein may offer a new strategy for cancer immunotherapy." (PMID 38545100, 2024). "We next tested two alternative hypotheses: either 7G5.TCR-T recognizes a cancer-specific/enriched ligand restricted by MR1*04 or binds preferentially to a ligand presented by all cells expressing the MR1*04 allele." (PMID 39445059, 2024). "Furthermore, self-reactive or cancer-reactive MR1-restricted T cells have been found in the blood of healthy individuals, whose reactivity was inhibited by 6-FP- or MR1-specific antibodies as MAIT cells." (PMID 39451228, 2024). "Later, a cancer-reactive TCR was shown to be restricted to an MR1 allele (MR1*04) and was not pan-cancer-reactive." (PMID 39451228, 2024).
cancer (continued). "Using IFN-γ as a measure of reactivity of 7G5.TCR-T to these cancer lines, we showed definitively that 7G5.TCR-T preferentially targets cells expressing the MR1*04 allele, while responses to over 100 MR1*01- and MR1*02-expressing cells were typically much weaker or nonexistent." (PMID 39445059, 2024). "Recently, self-reactive or cancer-reactive MR1-restricted T cells were identified in the blood of healthy individuals, but their antigens remained unknown." (PMID 39451228, 2024). "The discovery of the MR1-TCR offers therapeutic opportunities for many cancers in all individuals." (PMID 34650571, 2021). "Likewise, MR1 also represents an attractive target in immunotherapy against cancer, due to characteristics such as its monomorphic nature and functional expression found in several types of cancer cells." (PMID 33506055, 2021). "The identification of this protein by MR1-reactive T cells may mean a new therapeutic target for cancer immunotherapy and clearly places γδ T cells on the map as a promising and important T cell population." (PMID 34630403, 2021). "T cells expressing the MR1-restricted TCR (MR1-TCR) could kill a broad range of cancer cells independently of classical MHC molecules." (PMID 34650571, 2021). "In addition to knock out endogenous TCR genes, CRISPR/Cas9 system has also been used to identify a TCR that recognized and killed cancer cells in MHC-independent manner (via monomorphic MHC class I related protein, MR1)." (PMID 34095145, 2021). "Monomorphic MHC class I-related protein (MR1) has gained prominence after many discoveries about its regulatory role in mucosal-associated invariant T (MAIT) cell biology and its expression in cancer." (PMID 34630403, 2021). "Although high levels of MR1 expression should enhance cancer cell recognition, various tumors demonstrate MR1 overexpression with unknown implications." (PMID 33948562, 2021). "We also discuss therapeutic opportunities surrounding MR1-restricted T cells in cancer." (PMID 32411144, 2020). "While this was not a classical MAIT cell, it illustrates the potential significance of related lineages that are restricted by a monomorphic element such as MR1, as these cells are far more likely to have potential pan-cancer activity than HLA-restricted T cells." (PMID 32508830, 2020). "As MR1 is monomorphic and expressed in a wide range of cancer tissues, these findings raise the possibility of universal pan-cancer immunotherapies that are dependent on cancer metabolites." (PMID 32756356, 2020). "Recent publications report that atypical MR1-restricted cytotoxic T cells, differing from MAIT cells in TCR usage, antigen, and transcription factor profile, recognize an as yet unknown cancer-specific metabolite presented by MR1 in cancer cells." (PMID 32756356, 2020). "Studies have found that MR1 with presentation antigen can be recognized by some MR1-T cell clones in cancers and could be a promising target of cancer immunotherapy." (PMID 33185693, 2020). "In contrast, another recent report shows that a human T cell clone that recognizes an MR1 restricted nonbacterial antigen (potentially a cancer-specific or associated metabolite) mediates potent lysis of different cancer cell types." (PMID 32053875, 2020). "Recent publications report that a subpopulation of MR1-restricted cytotoxic T cells recognizes an as yet unknown cancer-specific metabolite presented by MR1 in cancer cells." (PMID 32756356, 2020). "On the other side, sensory pathways are being discovered which might give additional or alternative therapeutic angles, such as the recently identified MR-1 specific cancer-selective TCR clone." (PMID 32235616, 2020). "We also demonstrated that activated MAIT cells not only have LAK activity on cancer cells but they also have direct cytotoxicity, which may be mediated via degranulation of cytotoxic granules in both MR1-independent and MR1-dependent manners." (PMID 27517754, 2016).
cancer (continued). "This suggests that MR-1 may play a role in cancer progression by regulating cell adhesion and motility." (PMID 21702971, 2011). "The bias toward TRAJ42 use and conservation of a semi-invariant motif makes it tempting to speculate that the cells we describe across multiple donors likely exhibit limited antigen diversity and might bind to an identical MR1-bound cargo at the cancer cell surface." (PMID 39744940, 2025). "By analogy, MR1-restricted recognition of cancer may require a vitamin B6-derived neoantigen." (PMID 40763744, 2025). "MR1 however, is highly conserved across individuals and expressed in every human tissue, presents completely different classes of molecules, and will primarily bind to MAIT cells, eliminating the need to engineer a new TCR for each patient with a different cancer type or HLA allele." (PMID 33805904, 2021). "Interestingly, functional MR1 expression was found on several cancer cell types." (PMID 32053875, 2020). "MR1 can present self-antigens to MR1T cells, and a single MR1T cell can kill a wide range of cancer cell lines and primary cancer cells while remaining inert to healthy cells." (PMID 40362653, 2025). "Expression of either mR1 or mR1‐H12A in both E0771‐OVA and B16F10‐OVA cells reduced OT‐I T‐cell cytotoxicity against cancer cells." (PMID 39932384, 2025). "Novel discoveries of mammalian-derived agonists and antagonists binding to MR1 protein are our knowledge of MR1 ligand structures and functions from MAIT cell activation in healthy conditions to anti-cancer immunity." (PMID 40746558, 2025). "Although surface expression is generally low, MR1 expresses broadly across tissues at RNA and protein levels, and activates MAIT cells upon bacterial or cancer metabolite stimulation." (PMID 40746558, 2025). "This review will focus on MR1-restricted MAIT cells and diverse MR1T cells in cancer immunity, comparing their roles to other unconventional T cell subsets, including iNKT cells and γδ T cells." (PMID 40746558, 2025). "When considering that clone MC.27.759S possessed the only cancer-reactive TCR from the MR1-primed T cell lines from donor 0, then TRAJ42 constituted over 62% of cancer reactivity across all 7 donors." (PMID 39744940, 2025). "A distinct subset of MR1-restricted T cells (MR1T) has been identified with the apparent ability to specifically recognize and kill cancer cells." (PMID 39445059, 2024). "Thus, blocking MR-1 on cancer cells may help design MAIT-cells-based cancer immunotherapy." (PMID 37508372, 2023). "Other ideas include using TCR-technology to target multiple receptors on the target cell, MR1 and other MHC-presented antigens, in order to prevent immune-escape of cancer cells." (PMID 33805904, 2021). "These atypical MR1-restricted T cells (called MR1T), with their distinctive TCRs, represent a unique opportunity for the development of pan-cancer therapeutic agents." (PMID 32756356, 2020). "Given the recognition of multiple cancer cells lines by individual MR1T cell clones, it is feasible that cancers share common antigens presented by MR1." (PMID 32411144, 2020). "Our analysis also identified several antigen-presenting molecules as potential cancer drivers, including one class I (HLA-C), one class II (HLA-DRB1), and three HLA-like proteins (CD1C, CD1E and MR1)." (PMID 26485003, 2015). "Consistently, the data from the immunocompetent mice but not the NOD SCID mice revealed that expression of either mR1 or R1‐H12A in E0771 cells promoted cancer growth." (PMID 39932384, 2025). "Strategies aimed at reactivating exhausted MAIT cells, modulating MR1 antigen presentation, minimizing protumor MAIT cell subsets, and leveraging cytotoxic MAIT subsets or capabilities represent promising avenues for future cancer treatment." (PMID 40746558, 2025).
cancer (continued). "These cells recognized a wide range of cancer cell lines via MR1 regardless of what MR1 allomorph they expressed." (PMID 39744940, 2025). "This dependency suggests that the cancer-associated ligand(s) might form a Schiff base with this residue, as is known to occur with known microbial ligands, or, alternatively, might reflect changes in the MR1 antigen-binding pocket in the absence of the positively charged lysine residue." (PMID 39744940, 2025). "Jurkat cells expressing the MC.27.759S TCR responded to multiple cancer cell lines that naturally expressed either MR1*01 or MR1*02 but did not respond toward healthy CD14+ monocytes or CD19+ B cells from 3 donors." (PMID 39744940, 2025). "Cancer cell lines that were not MR1*04+, including Jurkat cells (MR1*01+/+), as used in the in vivo model in our previous study, were recognized well." (PMID 39744940, 2025). "MR1-restricted cancer-activated T cells are not MR1 allomorph-specific and do not react to healthy cells." (PMID 39744940, 2025). "Jurkat cells expressing MC.7.G5, MC.27.759S, K8T-1, or K8T-2 TCRs responded to MR1*01 homozygous or MR1*01/*02 cancer cell lines but, collectively, did not respond to monocytes or B cells from sixteen different healthy donors." (PMID 39744940, 2025). "All donors possessed T cell populations that activated in response to MR1+ cancer cell lines but not MR1-KO lines." (PMID 39744940, 2025). "Using a genome-wide CRISPR/Cas9 screen, Andrews found that the TCR recognizes and destroys cancer-specific cells through the antigen-presenting molecule MR1 (MHC class I-associated protein 1) and does not recognise recognise non-cancer cells." (PMID 39427211, 2024). "Ultimately, this led to the determination that 7G5.TCR-T was not cancer-specific but reactive to normal B cells and monocytes heterozygous for MR1*04." (PMID 39445059, 2024). "However, the link between MR1 expression and survival is complex and not universally clear across cancer types since he correlation between MR1 levels and MAIT cell infiltration differs among cancers." (PMID 38545100, 2024). "Jurkat cells expressing the MR1T cell-derived TCRs AVA34 or DGB129 showed no apparent reactivity to cancer cell lines with physiologic MR1 expression." (PMID 39445059, 2024). "Furthermore, GSVA analysis indicated significant enrichment of immunoactivation pathways in MR1, matrix‐related pathways in MR2 and multiple cancer‐promoting pathways in MR3." (PMID 38393307, 2024). "Given most studies to date with MR1-reactive T cells rely on MR1*01 overexpressing lines as targets, we next investigated whether 7G5.TCR-T could react to MR1*04-negative cancer lines engineered to express supraphysiological levels of the MR1*01 allele." (PMID 39445059, 2024). "The three TCR-T react to cancer cells heterozygous for MR1*04 and only marginally or not at all to cells that express only MR1*01 or are heterozygous for MR1*01/*02." (PMID 39445059, 2024). "Ligands require identification to ensure targeting MR1 is restricted to those specific to cancer and not normal tissues." (PMID 39445059, 2024). "Thanks to its ability to kill several cancer cell lines expressing low levels of MR1 while remaining inert towards noncancerous cells, this population represents a subset with a great potential for cell therapy approaches in several malignancies." (PMID 33723257, 2021). "They discovered that MR1 is one of the essential proteins needed for MR1T TCR-mediated targeting of cancer cells while sparing noncancerous cells." (PMID 32756356, 2020). "As MR1 is monomorphic and expressed in a wide range of cancer tissues, a future MR1T cell–based immunological therapy against all MR1-expressing cancers can be hypothesized and pursued by academia and industry." (PMID 32756356, 2020).
cancer (continued). "Lab tests have shown that T-cells enhanced with a special T-cell receptor (TCR) can destroy a wide range of cancer cells because the newly discovered TCR can recognize many types of cancer with the help of MR1 (which does not vary in human populations)." (PMID 32906638, 2020). "In an MR1-dependent manner, these MR1-restricted T cells, while sparing noncancerous cells, kill many cancer cell lines and attenuate cell-line-derived and patient-derived xenograft tumors." (PMID 32756356, 2020). "MR1-restricted T cells made from the MC.7.G5 clone can kill a broad range of cancer cells regardless of HLA." (PMID 33185693, 2020). "Designated “MR1T” cells, clones of these cells recognized, in the context of physiological levels of MR1 and dependent on MR1, endogenous cellular antigens from various tissues, including cancer tissues, and thus were not cancer specific." (PMID 33013835, 2020). "Subsequently, Crowther and co-authors identified TCR that recognises nonbacterial antigen presented by MR1 expressed on the surface of cancer cells." (PMID 32183246, 2020). "The TCR from MC.7.G5 T cell clone and the TCR from a similar clone, MC.27.759S, failed to confer a response to MR1-KO cancer lines and showed high dependence on the lysine residue at position 43 in MR1, which is known to form a Schiff base with the known MR1-presented bacterial ligands." (PMID 39744940, 2025). "No obvious patterns were seen within the TCR-β chain of MR1-restricted cancer-activated T cells." (PMID 39744940, 2025). "In addition, 23 of the 25 cancer cell targets tested during this study and recognized by MC.27.759S, MC.7.G5, K8T-1, or K8T-2 do not express MR1*04." (PMID 39744940, 2025). "MR1-restricted T-cell clones have also been identified, which could kill multiple cancer lines without recognizing healthy, noncancer cells, therefore raising the potential of translating TCR-based, MR1-restricted therapy for cancer patients." (PMID 39445059, 2024). "One potential clone, MC.7.G5, appeared to recognize a currently unknown cancer-specific molecule presented by the non-polymorphic protein MHC-related 1 (MR1)." (PMID 35720306, 2022). "Moreover, a recent study identified a new TCR that specifically kills many types of cancer cells via recognition of the non-polymorphic MHC class I-related protein (MR1)." (PMID 36483679, 2022). "Furthermore, we did not identify the existence of recently reported MR1-restricted T cells, which have been reported to recognize a broad range of cancer cells." (PMID 34489433, 2021). "One recent study identified an MR1 restricted T cell that could recognize and kill an assortment of autologous and non-autologous cancer cells, while remaining tolerant of healthy cells." (PMID 32508830, 2020). "The attractiveness of this discovery comes from the unvaried nature of MR1, due to its mandatory involvement in some microbial metabolism pathways, as well as MR1 expression on many cancer types cells but not healthy cells, which makes it a good candidate for ACT immunotherapy." (PMID 32973401, 2020). "This molecule attracts TCRs to infected cells, but it was not know if the MR1 molecule could attract TCRs to cancer cells too." (PMID 28518056, 2017). "Importantly, the MR1 that attracts these TCRs is the same in all people, and so the same TCR may recognize MR1-expressing cancer cells from different patients." (PMID 28518056, 2017). "The expression of MR1 in cancer has not been reported, making this a novel finding." (PMID 23251904, 2012). "For combined overexpression of PNKD in mice (cPD‐KI Kp mice), we found that MR‐1 can not only accelerate the progression and death of NSCLC, but also enable metastasis, while cPD‐KO Kp mice does not suffer from cancer." (PMID 38342606, 2024). "The cancer cell lines NCI-H1299, NCI-H2170, and SKLU1, all negative for MR1*04 expression, were chosen as they are poor targets for 7G5.TCR-T." (PMID 39445059, 2024).